INS (insulin)
Diseases named in the same sentence as INS in open-access papers (continued):
Sharing a sentence is not in itself a finding about the gene and the disease.
insulinoma (continued). "It has been demonstrated by previous studies and our group that treatment of insulinoma cells or isolated islets with cytokine mixtures reduces cell viability and insulin secretion in response to glucose." (PMID 28405188, 2017). "This diverse biology indicates a complex transformation of the insulinoma, despite the conserved function of insulin secretion." (PMID 28974674, 2017). "In the cell culture analyses of the present study, betulin and betulinic acid enhanced insulin-stimulated glucose uptake via PPAR-γ activity in adipocytes, whereas oleanolic acid potentiated glucose-stimulated insulin secretion in insulinoma cells." (PMID 26884795, 2016). "Constitutive expression of active Akt (Akttg) drives hyperplasia and hypertrophy of pancreatic β-cells, concomitantly with increased insulin secretion and improved glucose tolerance, and at a later stage the development of insulinoma." (PMID 26919188, 2016). "For example, insulin granules from rat insulinoma have a granular concentration of Ca2+ between 60 and 120 mM47." (PMID 27803801, 2016). "The laboratory tests used in case of suspicion of insulinoma are 72 hours fasting test with measurement of serum glucose, insulin and C-peptide concentrations." (PMID 27526057, 2016). "The process of insulin secretion has been studied in isolated rodent islets and beta-cell derived insulinoma cell lines." (PMID 26824039, 2016). "In insulinoma Min6 cells, insulin secretion was increased by 5.1 ± 0.7-fold in the high-glucose (20 mM) DMEM media compared with the low-glucose (2 mM) media." (PMID 26884795, 2016). "To further investigate the role of MAPT in insulin trafficking, we aimed to knock down endogenous Mapt gene in the Rin-5F insulinoma cell line." (PMID 26824039, 2016). "In this study we found that melatonin significantly regulated insulin production through the expression of GRP78/BiP protein which induced ER stress under conditions of 2-DG or 2-DG plus melatonin treatment in rat insulinoma INS-1E cells." (PMID 27493704, 2016). "Subsequently, an increase in intracellular insulin was measured in INS-1E insulinoma cells following treatment with the autophagy inhibitors, bafilomycin A1 and/or 3-methyladenine, in the presence or absence of 2-DG or rapamycin." (PMID 27536716, 2016). "The insulin suppressive effect is beneficial for patients who suffer from exaggerated secretion of insulin such as patients who have insulinoma or PCOS (Szkudelski, 2008)." (PMID 28096785, 2016). "Betulin potentiated insulin-stimulated glucose uptake via increased PPAR-γ activity and insulin signaling in 3T3-L1 adipocytes, whereas oleanolic acid enhanced glucose-stimulated insulin secretion and cell proliferation in insulinoma cells." (PMID 26884795, 2016). "Evidence for the direct effect of glucocorticoids on beta cell function has been found from cultured rat insulinoma insulin-secreting INS-1E cells." (PMID 27790079, 2016). "Through immunofluorescence, we detected the expression of Yap1 protein in rodent insulinoma cell lines, such as INS-1 832/13 and MIN6." (PMID 27000077, 2016). "For instance, Yoo and colleagues reported that melatonin regulates insulin synthesis through the endoplasmic reticulum (ER) via human antigen D (HuD) expression in rat insulinoma cells, and this was mediated by the activation of AMPK56." (PMID 27731378, 2016). "Insulin autoantibodies (IAA), glutamic decarboxylase antibodies (GADA), and insulinoma-associated protein -2 antibodies (IA-2) have been reported in diabetic dogs, but recent studies suggest that canine diabetes is not exclusively an autoimmune condition." (PMID 27031512, 2016). "For instance, overexpression of RORα in rat insulinoma cell lines increased expression and secretion of insulin." (PMID 26383638, 2015). "The tumor burden from these insulinomas is quantified clinically and in experimental models using plasma insulin concentrations." (PMID 26709830, 2015).
insulinoma (continued). "Due to the low malignancy and constant production of insulin by the tumor mass, insulinomas are usually detected due the systemic metabolic alterations that follow insulin oversecretion." (PMID 26347203, 2015). "The C-terminally extended peptide named TLQP-62 distinctly stimulated basal insulin secretion in several insulinoma cell lines." (PMID 26562304, 2015). "Cytopiloyne dose-dependently increased insulin mRNA expression and insulin secretion in rat insulinoma RIN-m5F cells, and calcium, diacylglycerol, and protein kinase Cα were shown to be involved in increased insulin secretion and production." (PMID 26587047, 2015). "Notwithstanding, a recent luciferase-based high-throughput screen identified Na+ channel modulators as potential regulators of insulin secretion in insulinoma cell lines, indicating that this area requires further study." (PMID 27019722, 2015). "Studies addressing the role of overexpressed ZnT7 in pancreatic insulinoma RIN5mf cells identified that glucose stimulation of these cells led to a significant increase in insulin secretion and subsequent insulin biosynthesis." (PMID 25983752, 2015). "Pancreatic islet cell adenomas with autonomous insulin production, commonly termed as insulinoma, are rare gastropancreatic neuroendocrine tumours (NETs) with an estimated incidence of 1 or 4 per million." (PMID 26558131, 2015). "To study Zip4’s function in zinc transport and insulin secretion in beta cells, we first used mouse insulinoma MIN6 cells." (PMID 25806541, 2015). "Ginsenoside Rb1, a principle active ingredients of Panax ginseng, has been shown to lower blood glucose in animals and increase insulin secretion in cultured insulinoma cells." (PMID 26300710, 2015). "Ectopic insulin secreting tumours are rare, comprising only 1% to 2% of all insulinomas and are commonly located in the peripancreatic or periduodenal region where most heterotopic pancreatic tissue is located." (PMID 24741994, 2014). "Insulinoma is a hormonally active tumor originating from insulin-synthesizing beta cells of the pancreas." (PMID 25202394, 2014). "In this study, we knocked down Prip or Gabarap in the MIN6 mouse insulinoma cell line using specific small interfering RNAs (siRNAs), and then analyzed glucose-induced insulin secretion from these cells." (PMID 24812354, 2014). "The INS-1 832/13 cells are rat insulinoma cells expressing human insulin with good glucose responsiveness, which are often utilized to investigate the physiological role of different human genetic findings." (PMID 25105407, 2014). "A recent study demonstrated that insulin and proinsulin were released in patients with insulinomas in response to arterial calcium stimulation, whereas CgA was not released." (PMID 25099181, 2014). "It was reported that pancreastatin, a CgA-derived peptide (CgA residues 250–301) with biological activity, inhibited the releasing of insulin by islet beta cells and insulinoma cell line." (PMID 25099181, 2014). "Since improvement of β-cell viability is a promising anti-diabetic strategy, the protective effect of metformin, a known insulin sensitizer was studied in rat insulinoma cells." (PMID 24896641, 2014). "Given the discovery of cell permeable small-molecule c-Abl tyrosine kinase activator, insulinoma can be potentially managed by using c-Abl activator to inhibit insulin production." (PMID 24835010, 2014). "Insulinoma is a rare tumor of the alimentary tract originating from insulin-synthetizing pancreatic beta cells." (PMID 25202394, 2014). "A similar decline of the exocytotic response is seen in rat beta-cells and rat insulinoma insulin-secreting INS-1 cells." (PMID 25105407, 2014). "Here, we investigated the role of PRIP in insulin granule exocytosis using Prip-knockdown mouse insulinoma (MIN6) cells." (PMID 24812354, 2014). "It was previously suggested that insulin levels >1,000 pmol/l argue against insulinoma and raise the suspicion of IAS." (PMID 25289063, 2014).
insulinoma (continued). "Donald Steiner, in elegant pulse-chase experiments, proposed the existence of proinsulin when he observed that a human insulinoma was producing higher MW forms of immunoreactive insulin, subsequently transformed into insulin-like material." (PMID 24167501, 2013). "Using the insulin-secreting rat insulinoma cell line INS-1E, we observed rapid mitochondrial shortening and recovery upon glucose stimulation." (PMID 23565276, 2013). "Diazoxide; an agent which suppresses the release of insulin from insulinoma cells via opening ATP-sensitive potassium channels, helps to prevent hypoglycaemia." (PMID 23738155, 2013). "When the insulinoma cells are bound to the portal vein, they work as a sensor to monitor the blood-sugar level and secrete insulin." (PMID 24069217, 2013). "In fact, we silenced PDK1 in clonal insulin–producing insulinoma cells, which lead to enhanced TCA cycle activity and insulin secretion." (PMID 23840896, 2013). "Studies in patients with metastatic insulin-secreting tumors (insulinomas) or with pancreatic islet cell transplants provide further evidence that insulin directly promotes fat accumulation in liver cells." (PMID 24264040, 2013). "The nonsecreting metastatic tumor in this patient transformed into a malignant insulinoma with dramatic insulin and proinsulin secretion." (PMID 26425568, 2013). "To confirm the direct effects of MW1219 on pancreatic β-cells, we examined glucose-stimulated insulin secretion by mouse pancreatic MIN6 insulinoma cells which endogenously express GPR119." (PMID 23704946, 2013). "While the majority of insulinoma tumors in RT2 mice express high levels of insulin, these highly invasive tumors were found to lack insulin expression, consistent with their poorly differentiated appearance." (PMID 23691228, 2013). "In this study, OXA (10−10 M to 10−6 M) is able to improve cell viability and promote insulin secretion via OX1R in INS-1 rat insulinoma cells." (PMID 24382962, 2013). "Viability of murine insulinoma cells was investigated by live-dead staining and live cell imaging, for murine Langerhans’ islets viability and insulin secretion have been measured." (PMID 24039964, 2013). "When staining for insulin, we found that while all mice had seven to ten insulinomas each, 70% of WT RT2 mice examined also had at least one PDIC." (PMID 23691228, 2013). "The metastatic lesions of an insulinoma generally secrete excessive insulin, identical to the primary tumor." (PMID 26425568, 2013). "A recent report has shown that MCU silencing impairs insulin secretion stimulated from clonal rat insulinoma cells, INS-1(832/13), by 16 mM glucose." (PMID 23149488, 2013). "This compound is described to have submicromolar binding affinity for the GLP-1 receptor and inhibit GLP-1 induced cAMP modulation and insulin secretion in RINmF5 insulinoma cells." (PMID 22611375, 2012). "We show that, like in pancreatic beta cells and insulinoma cell lines, also in neurons the expression level of Secretagogin is dependent on extracellular insulin and glucose." (PMID 22888312, 2012). "Both intraoperative serum glucose and insulin levels have been investigated, and rapid insulin immunoassay, from peripheral blood samples, has been proven in the literature reliably indicating successful removal of sporadic insulinoma." (PMID 24213321, 2012). "Overexpression of PDE3B in β-cells or insulinoma cells consequently reduces insulin secretion, whereas genetic down-regulation or pharmacological inhibition of the enzyme amplifies secretion, probably by regulating the most distal steps of granule fusion." (PMID 22970724, 2012). "NeuroD1 and PDX1 are OGlcNAcylated and translocated to nucleus under high-glucose conditions, exhibiting increased DNA-binding activity and promoting insulin gene expression and insulin secretion in mouse insulinoma 6 (MIN6) cells." (PMID 22110478, 2012).
insulinoma (continued). "Pharmacological inhibition or genetic down-regulation of PDE1 thus enhances glucose-stimulated insulin secretion both from insulinoma cells and pancreatic islets." (PMID 22970724, 2012). "M-60 and W-60 had greater glucose-stimulated insulin secretion capacity and greater β-cell viability than unfermented soybeans in insulinoma Min6 cells." (PMID 22550941, 2012). "In MEN1 insulinoma, the possible simultaneous presence of multiple pancreatic nodules makes it difficult to localize the lesion responsible for the increased insulin overproduction." (PMID 24213321, 2012). "In this study we show that the knockdown of the protein Eny2 results in increased glucose and incretin-stimulated insulin secretion from at baseline poorly responsive INS-1E insulinoma cells." (PMID 22649445, 2012). "Histopathological examination confirmed an islet cell adenoma, and the tumor was positive for insulin by immunostaining." (PMID 23243524, 2012). "Application of our reporter to presumably clonal HIT-T15 insulinoma cells, as well as other presumably clonal lines, indicates that these cultures are in fact heterogeneous with respect to INS+ phenotype." (PMID 22530041, 2012). "His investigations revealed low venous plasma glucose levels, high insulin and C-peptide levels and a 72-hour fast test that were all highly suggestive for an insulinoma." (PMID 23031644, 2012). "This molecule stimulates insulin secretion in INS-1E insulinoma cells and is selective against other class B1 GPCRs." (PMID 22611375, 2012). "Isolated islets from βTSC2−/− mice and TSC2 knockdown insulin 1 (INS-1) insulinoma cells treated with small interfering ribonucleic acid were used to investigate insulin secretion, ATP content and the expression of mitochondrial genes." (PMID 21886784, 2011). "The first study showing that the FFA oleate impaired insulin signaling in insulinoma cells demonstrated that the cells were protected from FFA-induced apoptosis by expressing a constitutively active Akt." (PMID 21541314, 2011). "Most patients with insulinomas present with neuroglycopenic symptoms and weight gain attributable to insulin excess." (PMID 21331288, 2011). "Further, the expression of miR-204 has been shown to be induced in insulinomas, where its expression correlated with insulin expression." (PMID 21294859, 2011). "To address this, we investigated the role of UFM1 and UFBP1 on insulin secretion in the rat glucose-responsive insulinoma cell line INS1-832/13." (PMID 21494687, 2011). "A mixed glucagonoma/insulinoma was present in one mouse although it had insulin levels comparable to those of other Gcgr−/− mice." (PMID 21853126, 2011). "ER stress in insulinoma cells was shown to impair insulin signaling through activation of ATF3, an ER stress response protein that was implicated in suppression of IRS2 expression." (PMID 21541314, 2011). "Our recent study showed that there was a dose-dependent effect of FFA in the presence of high glucose on apoptosis in insulinoma cells and primary islets that was associated with JNK activation, ER stress, and reduced insulin signaling." (PMID 21541314, 2011). "Pi and colleagues showed that addition of 1–4 μM H2O2 to mouse islets or insulinoma cells increases insulin secretion at low glucose levels." (PMID 21172424, 2011). "For the insulinoma cells, again all treatments resulted in a significant decrease in insulin immunoreactivity (p<0.001) compared to controls." (PMID 20804585, 2010). "We have previously shown that ChREBP silencing in pancreatic murine insulinoma MIN6 β-cells improves glucose-stimulated insulin secretion, possibly through a decrease in total triglyceride content." (PMID 20934404, 2010). "In mouse insulinoma cells pericentrin co-localized with insulin staining granules along the plasma membrane as shown by single z-sections taken at the ‘top’ and through the middle of the insulinoma cells." (PMID 20676397, 2010).
insulinoma (continued). "Insulinoma is an insulin–secreting tumor, benign (over 90% of cases) or malignant, single or multiple." (PMID 20968207, 2010). "Its expression is reported in insulinomas and directly correlates with immunohistochemical expression of insulin." (PMID 20302635, 2010). "Octreotide inhibits insulin secretion from both benign and malignant insulinomas via its effect on the G protein coupled somatostatin receptor." (PMID 20615254, 2010). "This resulted in reduction of intracellular insulin as shown by quantitation of insulin immunofluorescent intensities in insulinoma cells cultured in low (2.5 mM) glucose." (PMID 20676397, 2010). "PTBP1 (polypyrimidine tract-binding protein 1) is an RNA-binding protein that, in insulinoma INS-1 cells, enhances the stability and translation of mRNAs encoding insulin granule proteins." (PMID 21063464, 2010). "Usually, insulinomas are small sized, insulin secreting, benign tumors of the pancreas, and require surgical treatment." (PMID 20968207, 2010). "We used immunohistochemistry to address relative intracellular levels of insulin in Hit-T15 (pancreatic β-cell line) and Rin-m (insulinoma) cells." (PMID 20804585, 2010). "The Hit cells treated with 1 mM taurine contained more insulin than those treated with 3 mM glucose, suggesting that different mechanisms exist in normal β-cells than insulinoma cells with regard to sensitivity to taurine-regulated insulin release." (PMID 20804585, 2010). "Histochemical studies in human insulinomas showed that tumors have reduced insulin protein content compared with normal beta cells; hence it is possible that decreased storage capacity and uncontrolled hormone release are responsible for the hyperinsulinemia." (PMID 19545371, 2009). "We first developed an approach to generate insulinoma by transducing rat embryonic pancreatic epithelia with recombinant lentiviral vectors expressing the SV40T antigen under the control of the insulin promoter." (PMID 19266046, 2009). "Here, we report the morphological and cytogenetic features, as well as the biological behaviour, of three long term cultures of insulin producing human cells derived from two isolated insulinomas and one nesidioblastosis case." (PMID 19545371, 2009). "The in vitro culture of insulinomas provides an attractive tool to study cell proliferation and insulin synthesis and secretion." (PMID 19545371, 2009). "In view of the great demand for easily accessible beta cell lines for physiological and medical relevant studies, we set out to generate and characterize human insulin-releasing long term cell cultures derived from biopsies of insulinomas and nesidioblastosis." (PMID 19545371, 2009). "Glucose-regulated interactions between Hdac1/2, Pdx1 and/or Sox6 have been suggested to control insulin gene expression in mouse insulinoma cell lines." (PMID 18687323, 2008). "A similar concentration-dependent effect of Boc5 to amplify insulin secretion was observed in rat insulinoma INS-1E cells co-incubated with 16 mM glucose for 30 min." (PMID 18682834, 2008). "Some different tests can be used in order to show inadequate insulin secretion in cases that are suspected as insulinoma." (PMID 19040758, 2008). "Insulinoma is a neuroendocrine tumour derived mainly from the pancreatic islet cells producing excessive amounts of insulin." (PMID 19040758, 2008). "In conclusion, we present a confirmatory case demonstrating the utility of the rapid intraoperative insulin assay in facilitating intraoperative resection and confirmation of complete excision of insulinoma for the first time in a pediatric patient." (PMID 17958895, 2007). "In this case report we have presented a child with an insulinoma for whom intraoperative insulin measurements determined completeness of excision with subsequent cure." (PMID 17958895, 2007). "His glucose was 33 mg/dL with an insulin level equal to 21 U/dL, confirming the diagnosis of insulinoma." (PMID 17958895, 2007).